TNF (tumor necrosis factor)
Diseases named in the same sentence as TNF in open-access papers (continued):
Sharing a sentence is not in itself a finding about the gene and the disease.
tumor (continued). "Additionally, inflammation plays a role in this process, with inflammatory cytokines such as interleukin (IL)-6, IL-8, tumor necrosis factor (TNF) -α, and Prostaglandin (PGE) affecting the tumor microenvironment and potentially promoting tumor progression." (PMID 39050346, 2024). "We also observed that NR could increase the secretion levels of TNF-α and IFN-γ, suggesting that CD8+ T cells may have a stronger ability to kill tumor cells." (PMID 39519411, 2024). "However, in terms of the ratio of TNF+ to VEGFA+ MCs, the ratios of tissues at the tumor core (1.8) and tumor rim (1.2) were significantly lower than those of adjacent normal tissues." (PMID 39840068, 2024). "TNF-α usually plays an essential role in tumor treatment, which can directly kill tumor cells without significant toxicity to normal cells." (PMID 39065636, 2024). "Moreover, mast cell-derived PGD2 inhibits vascular leakage and regulates TNF-α production, thereby remodeling TME, and limiting tumor progression." (PMID 38704736, 2024). "PGLYRP1 was initially thought to be cytotoxic by itself for tumor cells and to function similarly to Tumor Necrosis Factor-α (TNF-α); further research showed that PGLYRP1 alone does not possess cytotoxic activity." (PMID 39204415, 2024). "Conjugating TNF-α with anti-EGFR antibodies, such as cetuximab, may be an effective immunocytokine therapy for tumours." (PMID 38789573, 2024). "Ablative UTMC was employed to explore immunogenic cell death in a TNBC model (4T1, immune excluded with low TMB); UTMC induced the translocation and expression of calreticulin and enhanced IL-12 and TNF-α, leading to increased infiltration of DC and CTL in both the tumor and TDLNs." (PMID 38543305, 2024). "Notably, hYP218 CAR T cells were maintained in an activated state in the tumour microenvironment, indicated by the expression of CD39 and CD69 markers along with increased IFNγ, and TNFα secretion." (PMID 39548594, 2024). "-Induction of TNF-α and IL-12p70 levels (in vitro).-Increased body weights of mice (decreased when NPs administered with adriamycin).-Increased serum TNF-α levels and CD4+/CD8+ lymphocyte ratios and decreased serum IL-10 levels (in vivo).-Increased tumor inhibition rate and decreased tumor growth." (PMID 39591094, 2024). "Changes in the expression and secretion profile of inflammatory mediators in CAAs, such as increased secretion of chemokines CCL2, CCL5, IL-6, TNF-α, VEGF, leptin, etc, will further promote the proliferation and invasion of tumor cells and the formation of new blood vessels." (PMID 39544302, 2024). "The platform’s adaptability was demonstrated through the development of a composite hydrogel system (MXene@agarose/TNF-α) that incorporates tumor necrosis factor-α (TNF-α) and enables the use of NIR light to modulate proapoptotic signaling in tumor spheroids in vitro." (PMID 38541577, 2024). "Although TNFR1 can be expressed in tumors, TNF-α signaling has not yet been demonstrated for CAR-M towards tumor cells as a cytotoxic effect." (PMID 39061247, 2024). "In addition, stroma-restricted CD8/CD4 T cells supply IFNγ and TNF/IL1 to the tumor nest, which further promotes tumor NOS2/COX2 expression at the tumor margin that leads to the formation of metastatic and CSC niches that are regionally distinct." (PMID 39356141, 2024). "Notably, more TNF‐α+, Perforin+, PD1+, and Ki‐67+ CD8+ T cells were detected in the RT group compared to the vehicle group, indicating a stronger tumor‐killing ability." (PMID 38286661, 2024). "We found that high dose IT mPH-762 generated tumor-specific memory CD8+ T cells in PLOs: these cells showed tumor-specific memory reactivity as marked by expression of intracellular IFN-γ and TNF-α induced by challenge with the same tumor cell line as had been treated IT in vivo (Hepa1-6)." (PMID 39697325, 2024).
tumor (continued). "Thus, 2pHLIP-dMSA induced transient tumor-targeted increases of type I interferon, IFN-β, and the pro-inflammatory cytokines TNF-α and IL-6, indicating activation of the NF-kB and IRF3 signaling pathways, without systemic activation." (PMID 38495104, 2024). "Moreover, ROS activate the mitogen-activated protein kinase (MAPK) pathway, which drives the production of pro-inflammatory cytokines like IL-1, IL-6, TNF-α, and TGF-β, leading to nuclear factor-kappa B (NF-κB) activation and tumor proliferation." (PMID 39766214, 2024). "Our results showed a significant increase in levels of expression of inflammatory cytokine IL-1 β (p < 0.01), IL-6 (p < 0.001), TNF-α (p < 0.001), and other related genes including TRAF6 (p < 0.01), MYD88 (p < 0.01), and GDF-15 (p = 0.005) in tumor-bearing mice compared to controls." (PMID 39394174, 2024). "M1 macrophages release proinflammatory cytokines, including nitric oxide synthase (iNOS), and tumor necrosis factor-alpha (TNF-α), and factors may lead to anti-tumor activity and induce the Th1 cells." (PMID 39582869, 2024). "A variety of cells of the immune response release pro-inflammatory cytokines, including IL-1β, IL-1α, TNFα, IL-6, IL-12, IFN-γ, and chemokines such as CCL2 and CXCL12, which participate in the initiation, growth, and progression of tumor and development of drug resistance." (PMID 38571491, 2024). "Moreover, CellChat analysis unveiled ligand-receptor pairs mediating communication between tumor epithelial cells and disulfidptosis-related TME subgroups, such as TNFSF12-TNFRSF12A, TNF-TNFRSF1A, OSM-(OSMR+IL6ST), OSM-(LIFR+IL6ST), HBEGF-EGFR, and EREG-EGFR." (PMID 38292868, 2024). "Our experiments showed that knockdown of circRHBDD1 increased the percentage and number of CD8+ T cells in tumor tissues, along with elevated expressions of cytokines IFN-γ, TNF-α, and granzyme B, and reduced levels of coinhibitory molecules PD-1, TIM-3, and LAG-3." (PMID 39080693, 2024). "Moreover, the production of cytokines such as IL-2, IL-4, IL-6, IL-7, IFN-γ, IFN-α, TNF-α, CCL7, and CCL28 can stimulate an anti-tumor response." (PMID 38533507, 2024). "It has been shown that inhibition of tumor acidosis by adenylyl cyclase inhibitor MDL-12 induces NOS, CXCL9, CXCL11, and TNF-α-expressing proinflammatory TAMs that are phenotypically similar to classical M1 macrophages, leading to suppression of tumor growth in B16 mouse melanoma." (PMID 39003350, 2024). "Furthermore, M1 macrophage polarization induces the production of pro-inflammatory cytokines such as TNF, IFN, and IL-1 in the TME of CRC, recruiting cytotoxic immune cells like CD8 + T cells and natural killer cells, thereby exerting anti-tumor effects." (PMID 38802814, 2024). "In this study, we demonstrated that the infection of B16F10 tumor cells with the rLaSota-BC-RFP virus increased the infiltration of CD8+ and CD4+ T cells in the tumor tissues, accompanied by elevated levels of IL-12, IFN-γ, IL-15, TNF-α, and IL-18." (PMID 39458338, 2024). "Tumor membrane‐coating PLGA NPs (NP‐R@M‐M) were developed with imiquimod (R837) and mannose modifications, and these NPs accelerated the maturation of DCs with higher levels of IL‐12 and TNF‐α production." (PMID 39713208, 2024). "To identify whether the knockdown of Aurora-A can influence the cytotoxic activity of tumor-infiltrating T cells, we analyzed IFNγ+/CD4+, IFNγ+/CD8+, and TNFα+/CD8+ T cell populations in tumors." (PMID 38291041, 2024). "SCC tissue and proximal healthy tissue also showed different responses to direct CP ex vivo, with higher levels of cytochrome c, higher IL10, TNFα, and IFNγ release, and lower IL22 released from tumour tissue indicating significantly increased stress and apoptosis in malignant tissues." (PMID 38785562, 2024). "B lymphocytes control cancer progression through cytokines like interferon-gamma and tumor necrosis factor-alpha while natural killer cells directly attach malignant tumor cells without the need for antigen activation." (PMID 39396135, 2024).
tumor (continued). "Oral administration of methacrylic acid (MAAc) linked with multi-walled carbon nanotubes (MWCNTs) and RSV (RSV-MWCNTs-MAAz) reduced inflammatory mediators TNF-α, IFN-γ, and IL-1βRSV-MWCNTs-MAAc showed more efficiency than free RSV due to prolonged RSV release at the tumor site." (PMID 38256959, 2024). "These proteins are essential for apoptosis (Bcl-xL, Bcl-2, c-IAP1, Mcl-1, c-IAP2, XIAP), the cell cycle (cdc-25, cyclins D1, B1 and A1), anti-tumor (ADAM10, HSP70, p21, Myc, RNA polymerase, p27) and inflammatory activities and immuno-regulation (TNF-a, IL-1, IL-4, IFN-a, IL-6, IL-2, CD80, CD40)." (PMID 38293343, 2024). "M1 macrophages secrete many cytokines, including interleukin 1-beta (IL-1β), tumor necrosis factor alpha and beta (TNF-α and TNF-β), and interleukin 6 (IL-6), and are regarded as anti-tumor or pro-inflammatory, while M2 are considered as pro-tumor or anti-inflammatory." (PMID 38842752, 2024). "Th17 cells are a veritable cytokine factory, producing a range of cytokines and chemokines, including IL-17A, IL-17F, IL-21, IL-22, TNF-α, and CCL20, which modulate the behavior of fibroblasts, endothelial cells, epithelial cells, macrophages, and tumor cells, thereby sculpting the TME." (PMID 39906741, 2024). "Furthermore, we analyzed the correlation between LINC00665 levels in metastatic lung cancer patients and immune-suppressive cytokines (TGF-β, IL-10, and IL-1β) as well as anti-tumor cytokines (IFN-γ, IL-2, and TNF-α)." (PMID 38951802, 2024). "Moreover, inflammatory markers, such as C-reactive protein (CRP), interleukin-6 (IL-6), and tumor necrosis factor-alpha (TNF-α), are elevated in CRC patients and correlated with tumor aggressiveness and poor prognosis." (PMID 38800241, 2024). "Although the TNFα level was not different in the tumor and the non-tumor groups (P > 0.9999), the IL-6 level was significantly high in the tumor group (P < 0.001)." (PMID 38166062, 2024). "Among the fourteen ferritinophagy-related genes studied, ten exhibited significant differences between tumor and normal samples: NCOA4, FTH1, FTL, SNCA (all p < 0.0001), BECN1 (p = 0.031), ELAVL1 (p = 0.00023), TNF (p = 0.00074), ATG16L1, ATG7, and ZFP36 (all p < 0.0001)." (PMID 39593730, 2024). "Inflammatory cytokines like TNF-α and IL-6 serve as a conduit for this communication and contribute to the recruitment of more inflammatory cells into the TME, increasing the growth and survival of genetically modified tumor cells." (PMID 38803729, 2024). "Cytokines such as tumor necrosis factor (TNF) and TGF-β are released by tumor cells." (PMID 39421736, 2024). "Enhanced growth may reflect the effect of T cell-derived TNF, which has been shown to enhance Panc02 PDAC tumor growth." (PMID 39178856, 2024). "The results indicated that SM-164 plus TNFα, but not SM-164 alone, significantly reduced tumor BLI signal levels in the bone." (PMID 39105847, 2024). "In addition to IFN-γ, activated NK cells also release tumor necrosis factor-α (TNF-α), which has been shown to upregulate the expression of inhibitory ligands PD-L1 and MHC-I in various tumor cell types." (PMID 39205244, 2024). "Exposure of MSCs to the pro-inflammatory cytokine TNF-α has been shown to upregulate CXCR4 expression, which may enhance the ability of MSCs to home to specific tissues, including tumours." (PMID 39062449, 2024). "Furthermore, cell death through CD8+ cytotoxic T cells and natural killer (NK) cells, as well as tumor cell senescence induced by CD4+ Th1 cells that produce IFN-γ and TNF-α, inhibits tumor growth." (PMID 38297164, 2024).
tumor (continued). "Post-treatment, the tumor microenvironment showed immunomodulatory changes, including altered macrophage infiltration and significant gene expression changes related to inflammation and immune response, such as IDO1, IL-6, TNF, CD209, and FOXP3." (PMID 39765586, 2024). "Ulrike Stein confirmed that after transducing tumor cells, IL2 and TNF modify treatment resistance." (PMID 38032489, 2024). "When CD8 T cells are activated, tumor necrosis factor-α (TNF-α) and interferon-γ (IFN-γ) are expressed, and antigenic peptides are specifically recognized through T cell receptors, which contribute to the elimination of tumor cells." (PMID 38248416, 2024). "Various death ligands, such as tumour necrosis factor (TNF)-α, Fas ligand, and TNF-related apoptosis-inducing ligand (TRAIL), are expressed on the membrane of CD8+ T cells or secreted from these cells and induce tumour cell apoptosis." (PMID 38893071, 2024). "The TNF (Tumor Necrosis Factor), also known as TNFα, is a cytokine that can directly kill tumor cells and has no significant cytotoxicity to normal cells, and induces cell survival or apoptosis by binding to two types of receptors (TNFR1 and TNFR2)." (PMID 38415010, 2024). "Additionally, the ratio of IFN-γ+, TNF-α+, or GZMB+ in tumor-infiltrating CD8+ T cells was decreased in MC38 tumors on Vegfb-cKO mice, whereas the cytokine production in these cytokine+ cells was not affected." (PMID 39145452, 2024). "This occurs via TNF-α-induced expression of endothelial cell-specific molecule-1 (ESM1), which regulates matrix metalloproteinase 9, VEGF, and delta like canonical Notch ligand 4 (DLL4), thereby contributing to tumor metastasis." (PMID 39337337, 2024). "Our results indicated no significant change in TNF-α expression between adjacent normal and tumor tissues." (PMID 39349746, 2024). "As previously reported, Probio-M9 substantially reduced the inflammatory response, infiltration of CD68+ macrophages in the non-tumor area, expression of TNF-α and IL-6, and number of Ki67-positive proliferating cells in the tumor area." (PMID 38540144, 2024). "Moreover, cigarette smoke was known to activate TNF-α, probably via cathepsins B mediated TNF-α-induced tumor cell death." (PMID 39280415, 2024). "Other ligand-receptor pairs revealed by this analysis included TNF-TNFRSF1A sent by medium-SORL1 expressing GAMs, TNFSF12-TNFRSF12A (high-SORL1 GAMs to tumor cells), PDGFB-PDGFRA (medium- and high-SORL1 GAMs to several populations), and THY1-(ITGAM + ITGB2) received by high-SORL1 GAMs (Fig. EV2B)." (PMID 38499808, 2024). "Inhibiting the PD-1/PD-L1 pathway can significantly boost the infiltration of CD4+ and CD8+ T cells in tumor cells, and effectively regulate the expression of a range of immune-related factors such as IL-2, IFN-γ, and TNF-α, thereby strengthening the body's anti-tumor immune function." (PMID 38312647, 2024). "However, the expression of TNFα and IFNγ in the CX3CR1+ subset was substantially lower than the CX3CR1− subset in the tumor." (PMID 38881188, 2024). "IFN-γ, TNF and IL-2 were found to be considerably increased by PPL-C when we assessed the cytokine concentration in cell culture supernatants, which further demonstrated that lymphocytes in immunotherapy-treated mice have been reactivated by tumor cells." (PMID 38745661, 2024). "Further examination of the TME utilizing flow cytometry disclosed that PHA-793887 markedly augmented the secretion of cytotoxic T cell-associated cytokines, including interferon-gamma (IFN-γ), tumor necrosis factor-alpha (TNF-α), and granzyme B (GZMB), within the tumor milieu." (PMID 39676867, 2024). "The developmental trajectory of IL1B+ TAMs has also been delineated; stimulation with IL-1 and TNF leads to the differentiation of monocytes into IL1B+ TAMs, which are primarily located around the tumor core in the matrix rich in CAFs and close to hypoxic areas within the tumor." (PMID 38982491, 2024).
tumor (continued). "Tregs can dampen T cell effector function, whereas CD4 helper T cells play a critical role in the development of anti-tumor immunity by assisting in the development of cytotoxic CD8 T cells, secreting anti-tumor cytokines such as IFNγ and TNFα, and stimulating B cell production." (PMID 39104861, 2024). "Through different time points analysis, we found that MSA-2 significantly stimulated TNF-α, IL-10, IL-6 and INF-β expression in both plasma and tumor and this expression reached the highest level around 4–6 days after MSA-2 injection and down to normal spectrum after 16 days." (PMID 38592428, 2024). "SIRPA blockade also rescued the numbers of CD8+ T cells and NKP46+ NK cells in tumour-bearing livers of Clec4fcreId3f/f mice, the formation of the peritumoural CD8+ T cell and NKP46+ NK-rich zone and the production of IFNγ and TNF by CD8+ T cells and NK cells." (PMID 38326607, 2024). "In addition, knocking out Rig-I enhanced the secretion of anti-tumour cytokines such as CD107a, perforin, granzyme-B, IFN-γ, and TNF-α by CD8+ T cells." (PMID 39322862, 2024). "Downregulation of NK cell-inhibitory receptors (NK-IRs) or upregulation of NK cell-activating receptors (NK-ARs) can trigger the release of TNF-α and interferon (IFN)-γ from NK cells, which in turn exert antibody-dependent cell-mediated cytotoxic effects to kill tumor cells." (PMID 38270700, 2024). "To investigate how the interaction between tumor cells and macrophages may impact LSD1 expression and TAM morphologies, we analyzed the expression of inflammatory cytokines TNFα and TGFβ, which are released by tumor cells within the tumor microenvironment." (PMID 38430255, 2024). "In addition, the frequencies of tumor necrosis factor (TNF)‐α+interferon (IFN)‐γ+, CD62L‐CD44+, and CD69+ tumor‐infiltrating CD8+ T cells were increased by anti‐PD‐1 mAb in tumors with APOC2‐K70R." (PMID 38981044, 2024). "In cancer patients, NK cells can recognize and eliminate tumor cells by releasing cytolytic molecules perforin and granzymes, as well as modulate the adaptive anti-tumor immune response by producing chemokines and cytokines such as IFN-γ, TNF-α, IL-8, IL-10, and CCL2." (PMID 38254110, 2024). "This highlights the synergistic effect between TGF-β1 and TNF-α in promoting tumor formation and proliferation in non-invasive BC epithelial cells." (PMID 39351229, 2024). "The release of inflammatory factors, such as TNF-a, IL-6, and MCP1, by the visceral fat of obese individuals induces localized chronic inflammation, thereby establishing a microenvironment that fosters tumor progression." (PMID 38829434, 2024). "The results of the study demonstrated that the administration of infliximab, as an anti-TNF-α agent, did not compromise the anti-tumor efficacy of ICIs." (PMID 39456702, 2024). "TNF‐α mRNA levels in skeletal muscle were not affected by the tumor, but heart levels increase on average without being statistically significant." (PMID 39294861, 2024). "Once interacting with the TLR7 on the cancer cell surface, this synthetic TLR activator can lead to the release of cytokines and chemokines such as tumor necrosis factor-alpha (TNF-α), interleukin-12 (IL-12), and IL-6, thus creating DC activation and specific tumor immune response." (PMID 39204409, 2024). "Moreover, MLT also improved the secretion levels of TNF-α and CXCL10 in macrophages, and the exosomes secreted by MLT-treated GC cells promoted the recruitment of CD8+ T cells to the tumor site, hence inhibiting tumor growth." (PMID 38455041, 2024). "Under radiation the nanoparticles repolarized MDSCs into M1 pro-inflammatory phenotype, producing a large amount of TNF-α and inducible nitric oxide synthase to relieve the suppression of CD8+ T cells in the inhibitory TME, which finally enhanced the anti-tumor efficacy." (PMID 38685033, 2024).